MEIG1 (meiosis/spermiogenesis associated 1)
Description:
Essential for spermiogenesis.
Synonyms: bA2K17.3; SPATA39
Tractability: No criterion of Open Targets' tractability assessment is met for any kind of drug.
Gene: Protein-coding gene on chromosome 10 (14,954,194 to 14,988,050, forward strand). Ensembl gene ENSG00000197889.
Gene Ontology:
Molecular function: protein binding
Cellular component: nucleus
Genetic constraint (gnomAD): Loss-of-function variants: 12 observed, 12.06 expected, observed/expected ratio (o/e) 0.99, 90% interval 0.64 to 1.59. The upper end of that interval is the gene's LOEUF score, 1.59, which puts it in group 6 of 6, group 1 being the genes least tolerant of losing a copy. Missense variants: 111 observed, 100.6 expected, observed/expected ratio (o/e) 1.1, 90% interval 0.94 to 1.29. Synonymous variants: 37 observed, 31.65 expected, observed/expected ratio (o/e) 1.17, 90% interval 0.9 to 1.54.
Homologues: Orthologues: chimpanzee MEIG1 (95% identical), dog MEIG1 (95% identical), macaque MEIG1 (95% identical), rabbit MEIG1 (95% identical), guinea pig MEIG1 (94% identical), pig MEIG1 (94% identical), rat Meig1 (92% identical), mouse Meig1 (88% identical), tropical clawed frog meig1 (80% identical), zebrafish meig1 (72% identical).
Diseases named in the same sentence as MEIG1 in open-access papers:
MEIG1 is named in the same sentence as 7 diseases in open-access papers, as found by Europe PMC text mining. Sharing a sentence is not in itself a finding about the gene and the disease. The quoted sentences say what the papers report.
male infertility (5 papers, 2016 to 2024). The inability of the male to effect fertilization of an ovum after a specified period of unprotected intercourse. "Disruption of either Meig1 or Pacrg in the male germ cells resulted in a similar phenotype of impaired spermiogenesis and male infertility." (PMID 37083624, 2023). "Though the MEIG1/PACRG complex has not been implicated in male infertility, it is known that asthenozoospermia, or low sperm motility, is found in 80%, to varying degrees, of infertile men." (PMID 34673028, 2021). "Five of these genes were characterized as male infertility‐related genes, including Polo‐like kinase 4 (PLK4), AGTPBP1, KISS1 receptor, Meiosis Expressed Gene 1 (MEIG1), and Piwi Like RNA‐Mediated Gene Silencing 2 (PIWIL2)." (PMID 37937809, 2024). "Global Meig1 knockout mice showed pure male infertility due to impaired spermiogenesis, but no meiosis defect was found." (PMID 34673028, 2021).
infertile (2 papers, 2021 to 2023). "Genetic disruption of Pacrg in mouse phenocopies the infertility phenotype of Meig1 knockout mice." (PMID 37083624, 2023). "However, no human MEIG1 mutations have been reported to be associated with infertility." (PMID 34673028, 2021).
premature ovarian failure (1 paper, 2015). "It has been reported that Meig1 is also expressed in embryonic mouse ovary, and MEIG1 mRNA expression is significantly altered in individuals with premature ovarian failure." (PMID 25715396, 2015).
sterility (1 paper, 2024). "Meig1 knockout in male mice results in sterility because of the arrest of spermiogenesis before the completion of spermatid elongation." (PMID 37937809, 2024).
infection (1 paper, 2024). The state of being infected such as from the introduction of a foreign agent such as serum, vaccine, antigenic substance or organism. "To address this point, we initially performed immunofluorescence experiments in transduced astrocytes 22 days post infection using antibodies against Centriolin (also known as Cep110), a known centrosomal marker, and Meig1 which was recently characterized as ependymal cell marker." (PMID 39468302, 2024).
MEIG1 also shares sentences with these, for which no sentence is quoted: asthenozoospermia (1 paper); teratozoospermia (1).